RNU6-1019P (RNA, U6 small nuclear 1019, pseudogene)
Gene: Small nuclear RNA gene on chromosome 20 (3,360,036 to 3,360,142, forward strand). Ensembl gene ENSG00000201294.
Homologues: Orthologues: chimpanzee U6 (100% identical), rat U6 (93% identical), pig U6 (90% identical), guinea pig U6 (88% identical), dog U6 (86% identical), rabbit U6 (85% identical), mouse Gm24430 (84% identical), mouse Gm22681 (80% identical), pig U6 (78% identical), macaque U6 (74% identical), mouse Gm25784 (59% identical). Paralogues in human: RNU6-41P (93% identical), RNU6-1060P (92% identical), RNU6-116P (91% identical), RNU6-12P (91% identical), RNU6-13P (91% identical), RNU6-15P (91% identical), RNU6-25P (91% identical), RNU6-31P (91% identical), RNU6-32P (91% identical), RNU6-33P (91% identical), RNU6-44P (91% identical), RNU6-536P (91% identical), and 1284 more.